GNA12 (G protein subunit alpha 12)
Description:
Guanine nucleotide-binding proteins (G proteins) are involved as modulators or transducers in various transmembrane signaling systems. Activates effector molecule RhoA by binding and activating RhoGEFs (ARHGEF12/LARG). GNA12-dependent Rho signaling subsequently regulates transcription factor AP-1 (activating protein-1) (By similarity). GNA12-dependent Rho signaling also regulates protein phosphatese 2A activation causing dephosphorylation of its target proteins. Promotes tumor cell invasion and metastasis by activating RhoA/ROCK signaling pathway and up-regulating pro-inflammatory cytokine production. Inhibits CDH1-mediated cell adhesion in process independent from Rho activation. Together with NAPA promotes CDH5 localization to plasma membrane. May play a role in the control of cell migration through the TOR signaling cascade.
Synonyms: gep; HG1M1; NNX3; RMP
Tractability: Antibody: UniProt places it where antibodies can reach, with high confidence; its Gene Ontology location is reachable by antibodies, with high confidence. PROTAC: ubiquitination databases record sites on it; its protein half-life has been measured.
Target class: Other membrane protein
Gene: Protein-coding gene on chromosome 7 (2,721,822 to 2,870,786, reverse strand). Ensembl gene ENSG00000146535.
Subcellular location: Cell membrane; Lateral cell membrane; Cytoplasm
Subcellular location (Human Protein Atlas): Cytosol
Pathways (Reactome):
Hemostasis: Thrombin signalling through proteinase activated receptors (PARs)
Signal Transduction: G alpha (12/13) signalling events
Gene Ontology:
Molecular function: G protein activity; protein binding; protein phosphatase 2A binding; protein phosphatase activator activity; D5 dopamine receptor binding; G-protein beta/gamma-subunit complex binding; GTPase activity; G protein-coupled receptor binding; guanyl nucleotide binding
Biological process: regulation of proteasomal ubiquitin-dependent protein catabolic process; regulation of TOR signaling; Rho-activating G protein-coupled receptor signaling pathway; adenylate cyclase-modulating G protein-coupled receptor signaling pathway; blood coagulation; G protein-coupled receptor signaling pathway; regulation of fibroblast migration; Rho protein signal transduction; regulation of blood pressure; response to xenobiotic stimulus; signal transduction
Cellular component: cytoplasmic side of plasma membrane; cytosol; focal adhesion; lateral plasma membrane; neuron projection; neuronal cell body; brush border membrane; plasma membrane; cytoplasm
Genetic constraint (gnomAD): Loss-of-function variants: 6 observed, 21.2 expected, observed/expected ratio (o/e) 0.28, 90% interval 0.15 to 0.56. The synonymous counts are far from expectation, so gnomAD's model fits this gene poorly and the ratio says little. Missense variants: 385 observed, 465.11 expected, observed/expected ratio (o/e) 0.83, 90% interval 0.76 to 0.9. Synonymous variants: 253 observed, 197.57 expected, observed/expected ratio (o/e) 1.28, 90% interval 1.15 to 1.42.
Homologues: Orthologues: chimpanzee GNA12 (100% identical), macaque GNA12 (99% identical), dog GNA12 (99% identical), mouse Gna12 (98% identical), pig GNA12 (98% identical), rat Gna12 (98% identical), guinea pig GNA12 (74% identical), Drosophila melanogaster cta (50% identical), Caenorhabditis elegans gpa-12 (47% identical), Caenorhabditis elegans gpa-16 (38% identical), Drosophila melanogaster Galphai (37% identical), Caenorhabditis elegans gpa-6 (36% identical), and 11 more. Paralogues in human: GNA13 (63% identical), GNAQ (42% identical), GNA11 (40% identical), GNA14 (39% identical), GNAO1 (39% identical), GNAI1 (38% identical), GNAI3 (38% identical), GNAT1 (38% identical), GNAT2 (38% identical), GNAT3 (38% identical), GNA15 (37% identical), GNAI2 (37% identical), and 3 more.